SHARPIN (SHANK associated RH domain interactor)
Diseases named in the same sentence as SHARPIN in open-access papers (continued):
Sharing a sentence is not in itself a finding about the gene and the disease.
Alzheimer disease (8 papers, 2019 to 2025). A progressive, neurodegenerative disease characterized by loss of function and death of nerve cells in several areas of the brain leading to loss of cognitive function such as memory and language. "To investigate the relationship between SHARPIN mutation and Aβ metabolism, we utilized an Alzheimer’s disease model HEK293 cell line (HEK-APPswe) widely employed in Aβ secretion studies." (PMID 38351238, 2024). "SHARPIN alone can also participate in many critical physiological activities and cause various disorders such as chronic dermatitis, tumor, and Alzheimer’s disease." (PMID 35547743, 2022). "We also found significant association of other SHARPIN variants with hippocampal volume in the Alzheimer’s Disease Neuroimaging Initiative (rs3417062, p = 4.1 × 10−6) and AddNeuroMed (rs138412600, p = 5.9 × 10−5) cohorts." (PMID 34785643, 2021). "SHARPIN is not only involved in the inflammatory response but also suppresses integrin activation and plays a key role in tumor cells and macrophages that cause Alzheimer’s disease." (PMID 35547743, 2022). "A recent study found that the onset of late Alzheimer’s disease (LOAD) may be associated with functional variants in SHARPIN." (PMID 35547743, 2022). "In addition to our previous report on rs572750141, a recent study by the ADNI (Alzheimer’s Disease Neuroimaging Initiative) reported a significant association of the SHARPIN coding variant rs34173062 (p.Ser17Phe) in GWAS with AD-vulnerable brain features." (PMID 34737388, 2022). "In this study, we identified known ADRD loci located in SHARPIN and TNIP1, along with nine novel risk loci − including KCTD13 – that are shared between Alzheimer’s disease and hippocampal volume." (PMID 40787599, 2025). "Here, we add six variants associated with Alzheimer’s disease risk (near APP, CHRNE, PRKD3/NDUFAF7, PLCG2 and two exonic variants in the SHARPIN gene)." (PMID 34099642, 2021). "In particular, we propose that loss of function mutations upstream of NF-κB such as ADAM17, SHARPIN, HOIL, or OTULIN affect NF-κB-activity in Alzheimer’s disease (AD) patients, in turn driving anatomical defects such as shrinkage of entorhinal cortex and the limbic system in early AD." (PMID 35983068, 2022).
hepatocellular carcinoma (5 papers, 2017 to 2023). A malignant tumor that arises from hepatocytes. "For instance, Fbxw7 regulates YAP protein stability by targeting YAP for ubiquitination and proteasomal degradation in hepatocellular carcinoma; SHARPIN and RNF187 promote YAP degradation via inducing YAP K48-dependent poly-ubiquitination." (PMID 37349820, 2023). "Normal human SHARPIN protein was initially found to locate in the cytoplasm, but employing immunohistochemistry in ovarian and hepatocellular carcinoma found SHARPIN expressed in both the cytoplasm and the nucleus." (PMID 35547743, 2022). "Similar to the findings in the mouse livers, reduced SHARPIN expression was observed in Hepa1-6 cells (mouse hepatoma cells) treated with APAP for 24 h." (PMID 28165393, 2017). "Furthermore, in good agreement with these in vivo results, transduction of Hepa1-6 hepatoma cells with SHARPIN, HOIL-1L, or HOIP shRNA adenovirus induced apoptosis of these cells in response to tumor necrosis factor-α (TNFα) stimulation." (PMID 28165393, 2017).
Immunodeficiency (5 papers, 2012 to 2022). Failure of the immune system to protect the body adequately from infection, due to the absence or insufficiency of some component process or substance. "Further structure and function study of SHARPIN genes and proteins will help to elucidate the pathogenesis of some tumors and some immune deficiency." (PMID 35547743, 2022). "Mice with spontaneous autosomal recessive mutations in the SHARPIN protein mainly exhibit chronic dermatitis and immunodeficiency with elevated IgM." (PMID 35547743, 2022). "However, the outcome of such a loss differs depending on the subunit: loss of HOIL- 1L causes embryonic lethality, whereas loss of SHARPIN develops severe auto-inflammatory disease and immunodeficiency in mice." (PMID 35547743, 2022). "However, the outcome of such a loss differs depending on the subunit: loss of HOIL-1L causes embryonic lethality, whereas loss of SHARPIN causes autoinflammation and immunodeficiency in mice." (PMID 29694895, 2018). "In this review, we summarize the now resolved structures of SHARPIN and its located LUBAC structure, introducing the cellular and physiological functions of LUBAC involvement and SHARPIN alone, including in immune diseases, tumors and other related diseases." (PMID 35547743, 2022). "Together, these results indicate an indispensible role of SHARPIN in regulating DC immunological functions, disruption of which may contribute to the development of immune diseases." (PMID 22348129, 2012). "In the human setting, loss of function mutations of HOIP, HOIL-1 or SHARPIN do not only result in autoinflammation, but also in immunodeficiency, glycogen storage disorders (HOIP and HOIL-1) and neurodegeneration (SHARPIN)." (PMID 35740456, 2022). "SHARPIN regulates TLR3-mediated innate immunity, auto inflammation and the development of immunodeficiency." (PMID 33255903, 2020). "Therefore, trace amounts of LUBAC comprise SHARPIN and HOIP and might be present in patients with immunodeficiency or autoinflammation, allowing these patients to be viable." (PMID 29694895, 2018). "Furthermore, mutant mice lacking SHARPIN develop severe autoinflammatory disease and immunodeficiency due to destabilization of the two remaining LUBAC subunits." (PMID 29694895, 2018).
prostate carcinoma (5 papers, 2015 to 2023). A carcinoma that arises from epithelial cells of the prostate gland. "SHARPIN expression is associated with poor prognosis in some other types of cancer; for example, SHARPIN-mediated activation of NF-κΒ signaling and the downstream targets survivin and livin promotes the progression and metastasis of prostate cancer." (PMID 37444594, 2023). "SHARPIN is modulator of the NF-kB pathway, and SHARPIN up-regulation promotes cell proliferation, migration, invasion and chemoresistance in prostate cancer by affecting the downstream targets survivin and livin." (PMID 26506596, 2015). "As a modulator of the NF-kB pathway, SHARPIN up-regulation promotes cell proliferation, migration, invasion and chemoresistance in prostate cancer by affecting the downstream targets survivin and livin." (PMID 26506596, 2015). "Furthermore, SHARPIN protein levels are elevated in prostate cancer and SHARPIN promotes cancer cell proliferation and tumor formation in several different cancer types." (PMID 26600301, 2015). "However, in PTEN-null PC3 prostate cancer cells SHARPIN also increased tumorigenicity implying that other functions, such as NF-κB signaling, are also involved." (PMID 26600301, 2015). "Previous reports have demonstrated a role for SHARPIN in Tumor Necrosis Factor (TNF, also known as TNFα) induced NF-κB activity in MEFs, keratinocytes, B-cells and hepatocytes, as well as in activated B-cell like diffuse large B-cell lymphoma, PC3 and DU145 prostate cancer cells." (PMID 26600301, 2015).
breast tumors (3 papers, 2015 to 2018). "In our study, we demonstrate that one ubiquitin binding protein SHARPIN, which is correlated with ERα expression in clinical breast tumor samples, potentiates ERα signaling activity and promotes tamoxifen resistance through post-translational modifications." (PMID 29100376, 2017). "SHARPIN was firstly cloned from nerve cells and was found to endure gene amplification in several human cancers, including breast tumor." (PMID 29100376, 2017). "We compared RNF31, RBCK1 and SHARPIN mRNA and protein expression in a subset of breast tumors." (PMID 29763465, 2018). "Correlation of ERalpha, RBCK1, RNF31 and SHARPIN mRNA expression levels in breast tumors." (PMID 29763465, 2018). "They found that SHARPIN mRNA expression levels are significantly elevated in invasive ductal breast carcinomas compared to non-tumor breast tissues and that the expression of this gene has an ability to discriminate breast tumors from non-tumor tissues (AUC = 0.83)." (PMID 29763465, 2018). "Particularly SHARPIN which was highly expressed in metastatic (Supplementary S3) and ERBB2 negative breast tumors." (PMID 26506596, 2015).
atopic dermatitis (2 papers, 2018 to 2020). "SHARPIN-deficient cpdm mice develop a chronic dermatitis with similarities to atopic dermatitis in humans." (PMID 29698466, 2018).
cervical cancer (2 papers, 2015). A primary or metastatic malignant neoplasm involving the cervix. "In DU145 prostate and HeLa cervical cancer cell lines these oncogenic effects were attributed to SHARPIN’s ability to inhibit PTEN function." (PMID 26600301, 2015).
cholangiocarcinoma (2 papers, 2023 to 2024). A carcinoma that arises from the intrahepatic biliary tree (intrahepatic cholangiocarcinoma) or from the junction, or adjacent to the junction, of the right and left hepatic ducts (hilar cholangiocarcinoma).
esophageal cancer (2 papers, 2021 to 2022). A primary or metastatic malignant neoplasm involving the esophagus. "On this basis, targeted inhibition of SHARPIN expression and activity may be a strategy for the treatment of esophageal cancer." (PMID 35547743, 2022).
fibrosarcoma (2 papers, 2020 to 2023). A malignant mesenchymal fibroblastic neoplasm affecting the soft tissue and bone. "With the exception of VAESBJ (epithelioid sarcoma), HT1080 (fibrosarcoma), and SW872 (liposarcoma) cells, the expression level of the SHARPIN mRNA in the other sarcoma cell lines was higher than that in HDF, although it was also expressed at a high level in 293T and HeLa cells." (PMID 37444594, 2023). "Treatment with TNF resulted in the formation of the TNF receptor signalling complex‐I (TNFR‐SC, also referred to as complex‐I) in the human fibrosarcoma cell line HT1080, as evidenced by the recruitment of bona fide TNFR‐SC components such as RIPK1, SHARPIN and TRADD (Fig EV2A)." (PMID 32419365, 2020).
lung carcinoma (2 papers, 2017 to 2023). "Since PRMT5 is also required for mediating the molecular consequences of EMT, these observations strongly suggested that SHARPIN is essential for maintaining PRMT5-associated chromatin environments in lung cancer A549 cells, with the activation of expression of cancer metastasis-related genes." (PMID 28903384, 2017). "However, whether SHARPIN plays an important role in lung cancer metastasis and the potential underlying mechanism are still unknown." (PMID 28903384, 2017). "To explore the mechanism by which SHARPIN regulates lung cancer cell invasion, we attempted to identify new potential cofactors interacting with SHARPIN." (PMID 28903384, 2017). "This exciting observation was also supported by results showing that SHARPIN RNA and protein expression is increased in several common lung cancer cell lines compared with those in normal lung cells." (PMID 28903384, 2017). "Immunoblots for SHARPIN confirmed efficient knockdown of SHARPIN in different lung cancer cells including A549, H460 and SK-MES-1 cells." (PMID 28903384, 2017). "Here, for the first time, we reported that SHARPIN expression is closely related to lung cancer progression." (PMID 28903384, 2017). "To explore the pathologic role of SHARPIN in regulating cancerogenesis, in the present study, we report for the first time that SHARPIN expression is upregulated in lung cancer." (PMID 28903384, 2017). "We further showed that SHARPIN plays a novel role in lung cancer metastasis." (PMID 28903384, 2017). "Moreover, SHARPIN plays a central role in controlling lung cancer cell metastasis." (PMID 28903384, 2017). "We demonstrate that the interaction with SHARPIN with a novel cofactor PRMTA5 plays biological roles in tumor progression and invasion via regulating a unique histone H3R2 methylation-coupled transcriptional activation in lung cancer cells." (PMID 28903384, 2017).
sarcoma (2 papers, 2021 to 2023). A usually aggressive malignant neoplasm of the soft tissue or bone. "We found that SHARPIN expression was significantly associated with reduced survival in cohorts of patients with cancer, including sarcoma." (PMID 37444594, 2023). "Analysis of a sarcoma-specific cohort (n = 265) revealed that SHARPIN gene amplification and/or high mRNA expression was significantly associated with shorter OS (p < 0.05) and PFS (p < 0.05)." (PMID 37444594, 2023). "A recent study demonstrated that NF-κΒ activation is required to trigger ferroptosis; therefore, we investigated the influence of SHARPIN on the prognosis of sarcoma and the sensitivity of sarcoma cells to ferroptosis." (PMID 37444594, 2023). "Because NF-κB can provoke ferroptosis, we examined the role of SHARPIN, an activator of NF-κB, in sarcoma." (PMID 37444594, 2023). "Furthermore, analysis of TCGA datasets indicated that high SHARPIN expression is significantly related to poor prognosis in all types of cancer, including sarcoma, suggesting the importance of SHARPIN in clinical practice." (PMID 37444594, 2023). "In addition to TFRC, SHARPIN mRNA expression was also higher in various sarcoma cell lines, except VAESBJ, SW872 and HT1080." (PMID 37444594, 2023). "As an activator of NF-κΒ, SHARPIN plays a role in cancer progression; therefore, we hypothesized that it may impact the prognosis of sarcoma." (PMID 37444594, 2023). "SHARPIN promotes the sensitivity of sarcoma cells to ferroptosis." (PMID 37444594, 2023). "In addition, SHARPIN promoted the sensitivity of sarcoma cells to ferroptosis." (PMID 37444594, 2023). "Taken together, these findings highlight the impact of SHARPIN on clinical outcomes such as OS and DFS, particularly in sarcoma." (PMID 37444594, 2023). "Based on the results presented above, we propose that sarcoma is characterized by increased expression of TFRC and SHARPIN, with high GPX4 dependency, suggesting that ferroptosis may be a promising therapeutic target for sarcoma." (PMID 37444594, 2023). "Overall, our findings suggest that ferroptosis may be a promising therapeutic target in sarcoma, particularly in subpopulations with poor prognosis due to high TFRC and SHARPIN expression." (PMID 37444594, 2023). "In summary, we suggest that ferroptosis could be a therapeutic target in sarcoma, particularly in subpopulations with high TFRC and SHARPIN expression." (PMID 37444594, 2023). "Our findings suggest that ferroptosis could have a therapeutic effect in sarcoma, particularly in subpopulations with high TFRC and SHARPIN expression." (PMID 37444594, 2023). "In addition, TFRC and SHARPIN were expressed at higher levels in sarcoma cell lines than in noncancer and carcinoma cell lines." (PMID 37444594, 2023).
soft tissue sarcoma (2 papers, 2021 to 2023). A malignant neoplasm arising from muscle tissue, adipose tissue, blood vessels, fibrous tissue, or other supportive tissues excluding the bones. "According to the CCLE database, high SHARPIN mRNA expression is significantly associated (High vs Middle, p < 0.005; High vs Low, p < 0.05) with high GPX4 dependency in a bone and soft tissue sarcoma cohort." (PMID 37444594, 2023). "Amplification of the SHARPIN gene was associated with shorter PFS and OS in soft tissue sarcoma, as shown by TCGA database analysis." (PMID 34178683, 2021).
Stroke (2 papers, 2025). Sudden impairment of blood flow to a part of the brain due to occlusion or rupture of an artery to the brain. "Intriguingly, a human genetic variant of SHARPIN (rs117299156_C) was associated with lower risk of stroke in patients with myocardial infarction, suggesting that reduced SHARPIN activity may have protective cardiovascular effects." (PMID 40149956, 2025). "For example, mechanisms that affect fibrosis and vascular remodeling, such as those involving SHARPIN protein, have been shown to impact stroke and cardiovascular outcomes." (PMID 40162014, 2025).
viral infections (2 papers, 2023 to 2024). "Comparison of the relative contribution of the three separate LUBAC components therefore defines both HOIP and HOIL-1 as being essential for RIG-I signalling and for the IFN response to virus infections, but SHARPIN as dispensable for this process." (PMID 38001254, 2024). "We focused on SHARPIN and RNF5 as candidate hits for ORF3, as they are involved in the RLR-MAVS pathway and interferon (IFN) induction during viral infections." (PMID 38140653, 2023).
adenovirus infection (1 paper, 2017). "In addition to such endogenous inflammatory stimuli, it is possible that adenovirus infection, as used in our experiments, may contribute to apoptosis by functioning as a trigger, when HOIP or SHARPIN expression is suppressed." (PMID 28165393, 2017).
autoinflammatory syndrome (1 paper, 2019). A group of disorders of the innate immune system characterized by attacks of seemingly unprovoked inflammation without significant levels of either autoantibodies or autoreactive T cells more characteristic of autoimmune disease. "SHARPIN‐deficient cpdm (chronic proliferative dermatitis) mice and patients with mutations in HOIP or HOIL‐1 develop severe autoinflammatory syndromes." (PMID 30804083, 2019).
BOR syndrome (1 paper, 2022). "The BOR syndrome was demonstrated in zebrafish after the knockdown of SHARPIN, implying SHARPIN plays a role in bone and craniofacial formation." (PMID 35547743, 2022).
cardiomyopathy (1 paper, 2024). A disease of the heart muscle or myocardium proper. "Cardiomyopathy and myopathy have been observed only in HOIL-1L-deficient patients; therefore, it is unlikely that SHARPIN, HOIP, and the LUBAC are also involved in these pathologies." (PMID 38632277, 2024).
esophageal squamous cell carcinoma (1 paper, 2021). Esophageal squamous cell carcinoma (ESCC) is a type of esophageal carcinoma (EC) that can affect any part of the esophagus, but is usually located in the upper or middle third. "However, SHARPIN inhibits esophageal squamous cell carcinoma progression." (PMID 34178683, 2021).
facial paralysis (1 paper, 2023). Severe or complete loss of facial muscle motor function. "Expression of shank-associated RH domain-interacting protein (SHARPIN) is upregulated in the brainstem of mice with herpes simplex virus-1 (HSV-1)-induced facial paralysis." (PMID 37237902, 2023).
Fulminant hepatitis (1 paper, 2017). Acute hepatitis complicated by acute liver failure with hepatic encephalopathy occurring less than 8 weeks after the onset of jaundice. "SHARPIN expression and LUBAC formation were significantly reduced in the livers of mice 24 h after the injection of either carbon tetrachloride (CCl4) or acetaminophen (APAP), both of which produced the fulminant hepatitis phenotype." (PMID 28165393, 2017).
glioblastoma (1 paper, 2025). The most malignant astrocytic tumor (WHO grade IV). "We detected that SHARPIN expression strongly correlates with MGMT expression in glioblastoma patients." (PMID 39936970, 2025). "Firstly, we performed a Kaplan–Meier estimator survival analysis with 220 cases of glioblastoma (IDH WT and mutated); of these cases, 109 had high expression of SHARPIN, and 111 had low expression of the marker." (PMID 39936970, 2025). "As with SHARPIN, we detected that TMEM173 expression strongly correlates with MGMT expression in patients with glioblastoma." (PMID 39936970, 2025).